ZNF184 (zinc finger protein 184)
Description:
May be involved in transcriptional regulation.
Synonyms: kr-ZNF3
Tractability: PROTAC: UniProt records ubiquitination sites on it; ubiquitination databases record sites on it.
Gene: Protein-coding gene on chromosome 6 (27,450,743 to 27,473,141, reverse strand). Ensembl gene ENSG00000096654.
Subcellular location: Nucleus
Subcellular location (Human Protein Atlas): Nucleoplasm
Pathways (Reactome):
Gene expression (Transcription): Generic Transcription Pathway
Gene Ontology:
Molecular function: DNA-binding transcription factor activity, RNA polymerase II-specific; RNA polymerase II cis-regulatory region sequence-specific DNA binding; zinc ion binding
Biological process: regulation of transcription by RNA polymerase II; regulation of DNA-templated transcription
Cellular component: nucleoplasm; nucleus
Genetic constraint (gnomAD): Loss-of-function variants: 18 observed, 63.46 expected, observed/expected ratio (o/e) 0.28, 90% interval 0.19 to 0.42. The synonymous counts are far from expectation, so gnomAD's model fits this gene poorly and the ratio says little. Missense variants: 679 observed, 936.42 expected, observed/expected ratio (o/e) 0.73, 90% interval 0.68 to 0.77. Synonymous variants: 254 observed, 313.72 expected, observed/expected ratio (o/e) 0.81, 90% interval 0.73 to 0.9.
Homologues: Orthologues: chimpanzee ZNF184 (99% identical), macaque ZNF184 (99% identical), pig ZNF184 (93% identical), dog ZNF184 (93% identical), rabbit ZNF184 (87% identical), zebrafish znf646 (24% identical), zebrafish si:dkey-89b17.4 (23% identical), zebrafish znf576.1 (23% identical), Drosophila melanogaster CG30020 (18% identical), Drosophila melanogaster mld (16% identical), zebrafish zgc:66472 (15% identical), Drosophila melanogaster az2 (15% identical), and 6 more. Paralogues in human: ZNF91 (49% identical), ZNF160 (49% identical), ZNF420 (48% identical), ZNF84 (48% identical), ZNF107 (46% identical), ZNF347 (46% identical), ZNF208 (45% identical), ZNF569 (45% identical), ZNF99 (44% identical), ZNF729 (44% identical), ZNF845 (42% identical), ZNF594 (41% identical), and 24 more.
Diseases named in the same sentence as ZNF184 in open-access papers:
ZNF184 is named in the same sentence as 12 diseases in open-access papers, as found by Europe PMC text mining. Sharing a sentence is not in itself a finding about the gene and the disease. The quoted sentences say what the papers report.
depression (4 papers, 2021 to 2024). "Finally, ZNF184 has been previously proposed as a key gene in the genetic architecture underlying major depressive disorder in GWAS and meta-analysis studies." (PMID 39727940, 2024). "Nevertheless, some other relevant overexpressed genes detected after CASh analysis of the major depression datasets include EXOSC2 (Exosome Component 2), DPP10 (Dipeptidyl Peptidase Like 10), GSTM5 (Glutathione S-Transferase Mu 5), and ZNF184 (Zinc Finger Protein 184)." (PMID 39727940, 2024).
Parkinson disease (3 papers, 2018 to 2021). A progressive degenerative disorder of the central nervous system characterized by loss of dopamine producing neurons in the substantia nigra and the presence of Lewy bodies in the substantia nigra and locus coeruleus. "Furthermore, a study performed by the International Parkinson’s Disease Genomics Consortium showed 24 novel risk loci for PD in the European population; and 17 risk loci for PD in ITPKB and ZNF184 were identified in a study with East Asians." (PMID 34576000, 2021).
acute lymphoblastic leukemia (1 paper, 2026). Leukemia with an acute onset, characterized by the presence of lymphoblasts in the bone marrow and the peripheral blood. "Through integrative analysis of bulk and single-cell RNA sequencing data, we identified a conserved set of seven ZNF genes, including ZNF184, that are upregulated in acute lymphoblastic leukemia (ALL) and exhibit dynamic expression patterns linked to disease progression." (PMID 42165129, 2026).
Alzheimer disease (1 paper, 2021). A progressive, neurodegenerative disease characterized by loss of function and death of nerve cells in several areas of the brain leading to loss of cognitive function such as memory and language. "The list included several known disease genes, such as INPP5D (Alzheimer’s disease), RAB27B (major depressive disorder, MDD), SORL1 (Alzheimer’s disease) and ZNF184 (MDD and schizophrenia)." (PMID 34446921, 2021).
autoimmune disease (1 paper, 2021). A disorder resulting from loss of function or tissue destruction of an organ or multiple organs, arising from humoral or cellular immune responses of the individual to their own tissue constituents. "ZNF184 is in the extended major histocompatibility complex (MHC) region, which plays a complex but important role in both neurodegenerative and autoimmune diseases." (PMID 33541344, 2021).
esophageal squamous cell carcinoma (1 paper, 2025). Esophageal squamous cell carcinoma (ESCC) is a type of esophageal carcinoma (EC) that can affect any part of the esophagus, but is usually located in the upper or middle third. "Although ZNF184 has been investigated in other diseases such as esophageal squamous cell carcinoma (ESCC), its role in PD remains relatively unexplored." (PMID 40333790, 2025).
hyperhomocysteinemia (1 paper, 2018). A serious metabolic condition caused by mutations in the MTHFR gene, medications, or nutritional deficiency. "The relationship between ZNF184, hyperhomocysteinemia and PD still needs to be investigated further." (PMID 30618709, 2018).
Obesity (1 paper, 2025). Accumulation of substantial excess body fat. "The intronic variant, rs140919115 (n.265 + 6212G > A), located in ZNF184 was associated with Obesity Class III." (PMID 40939575, 2025).
neurodegenerative disease (1 paper, 2025). A disorder of the central nervous system characterized by gradual and progressive loss of neural tissue and neurologic function. "Future research should focus on the direct regulatory mechanisms of ZNF184, its interactions with ROS and transcription factors, and its therapeutic application in neurodegenerative diseases." (PMID 40333790, 2025).
ZNF184 also shares sentences with these, for which no sentence is quoted: choriocarcinoma (1 paper); lung carcinoma (1); tumor (1).